ASCL5 (achaete-scute family bHLH transcription factor 5)
Description:
Transcription factor. Probably binds E-box motifs 5'-CANNTG-3' in complex with transcription factor TCF3/E12. Negatively modulates transcription of target genes such as CDH1/E-cadherin, perhaps by recruiting the PRC2 repressive complex to regulatory elements. Regulates ameloblast development and tooth germ growth, perhaps acting by positively modulating migration of inner enamel epithelium (IEE) cells. Plays a role in enamel formation.
Synonyms: ASH-5; bHLHa47; AmeloD; LBDT
Gene: Protein-coding gene on chromosome 1 (201,113,943 to 201,127,184, reverse strand). Ensembl gene ENSG00000232237.
Subcellular location: Nucleus
Genetic constraint (gnomAD): Loss-of-function variants: 0 observed, 1.06 expected, observed/expected ratio (o/e) 0, 90% interval 0 to 1.7. That is too few expected variants to judge how well the gene tolerates losing a copy. Missense variants: 261 observed, 243.48 expected, observed/expected ratio (o/e) 1.07, 90% interval 0.97 to 1.19. Synonymous variants: 124 observed, 115.82 expected, observed/expected ratio (o/e) 1.07, 90% interval 0.93 to 1.24.
Homologues: Orthologues: chimpanzee ASCL5 (98% identical), macaque ASCL5 (97% identical), mouse Ascl5 (72% identical), rat Ascl5 (72% identical), pig ASCL5 (68% identical), dog ASCL5 (62% identical), Drosophila melanogaster ase (24% identical), Drosophila melanogaster sc (22% identical), Drosophila melanogaster l(1)sc (21% identical), Drosophila melanogaster ac (17% identical), Caenorhabditis elegans hlh-14 (17% identical). Paralogues in human: ASCL4 (32% identical), ASCL3 (31% identical), ASCL1 (26% identical), ASCL2 (24% identical).
Diseases named in the same sentence as ASCL5 in open-access papers:
ASCL5 is named in the same sentence as 5 diseases in open-access papers, as found by Europe PMC text mining. Sharing a sentence is not in itself a finding about the gene and the disease. The quoted sentences say what the papers report.
alopecia (1 paper, 2022). Hair loss usually from the scalp. "In the top 10 up-regulated DEGs, SHISA7 (shisa family member 7) and ASCL5 (achaete-scute family bHLH transcription factor 5) were 10 and sixfold higher in alopecia males than normal males, respectively." (PMID 35413801, 2022).
cancer (2 papers, 2021 to 2022). A tumor composed of atypical neoplastic, often pleomorphic cells that invade other tissues. "Other IGs discussed in this study and linked with cancer and neurodevelopmental disorders were Pou3f3, bHLHE22, ASCL5, and Hist2h2be." (PMID 34306008, 2021). "Several ACSLs-related reviews have summarized the mechanisms and function of the ACSLs in cancer: ACSL1 and ACSL3 may lead to cancer progression and worse prognosis, while ASCL5 and ACSL6 act as key suppressor with the opposite effect." (PMID 36507355, 2022).
ASCL5 also shares sentences with these, for which no sentence is quoted: COVID-19 (1 paper); neurodevelopmental disorder (1); tumor (1).